CCND1 (cyclin D1)
Diseases named in the same sentence as CCND1 in open-access papers (continued):
Sharing a sentence is not in itself a finding about the gene and the disease.
laryngeal carcinoma (26 papers, 2008 to 2024). Carcinoma that arises from the laryngeal epithelium. "Our results show that Cyclin D1 protein expression was significantly associated with a shorter survival time in laryngeal cancer patients, which is similar to the results of other studies." (PMID 35626215, 2022). "Our purpose was to investigate the utility of the CCND1 genotyping and Cyclin D1 expression in predicting susceptibility of transformation from normal tissue to precancerous laryngeal lesions (PLLs) and to laryngeal cancer (LC)." (PMID 35626215, 2022). "Obtained results show that the expression of Cyclin D1 has an important role in the progression of premalignant lesions to laryngeal cancer." (PMID 35626215, 2022). "Recently, the team of Xi Tan has reported that ECD inhibits the growth of laryngeal carcinoma via the STAT3/Cyclin D1 pathway and it was the first study on the mechanism of ECD in the treatment of tumors." (PMID 36313338, 2022). "Based on a review of published studies, it has been demonstrated that downregulation of miR-34a promotes laryngeal cancer cell proliferation and migration by targeting cyclin D1." (PMID 34158050, 2021). "For example, HPV16 E7 protein can activate the cell cycle regulation protein D1 (cyclin D1), thereby accelerating the G1-to-S phase in cells and leading to the occurrence and development of laryngeal cancer." (PMID 31528209, 2019). "Moreover, patients with Cyclin D1 expression index above 15% (a cut-off point) were three times more likely to die from laryngeal cancer." (PMID 35626215, 2022). "Allele A CCND1 G870A polymorphism carriers and Cyclin D1 protein overexpression did not affect laryngeal cancer recurrence." (PMID 35626215, 2022). "Furthermore, hsa-miR-21 modulates cell cycle through regulation of BTG family member 2, a transcriptional coregulator of the cyclin D1 promoter that is dysregulated in laryngeal cancer." (PMID 21569500, 2011). "Recent studies also revealed that the expression of Cyclin D1 protein was correlated with tumor stage, metabolic volume of tumor, glycolysis in lesion and maximum standardized uptake value (SUV max) in patients diagnosed with laryngeal cancer and was suggested as a diagnostic and follow-up marker." (PMID 35626215, 2022). "Therefore, the expression of HPV16 E7 and cyclin D1 must be detected in laryngeal cancer tissues for early diagnosis and early treatment of laryngeal cancer, and both can also be used as biomarkers to determine the malignant degree and prognosis of laryngeal cancer." (PMID 31528209, 2019). "High cyclin D1 expression was observed in laryngeal carcinomas, and the positive correlation between phosphorylated STAT3 (p‐STAT3) protein and cyclin D1 mRNA suggests that STAT3 promotes cyclin D1 transcription in laryngeal carcinogenesis." (PMID 36419252, 2023). "We first examined the protein levels of the key molecular markers, including cyclin D1, Wnt4, MYC, Wnt7A, and Wnt9A, of the Wnt/β-catenin signaling pathway in laryngeal carcinoma cells." (PMID 33060569, 2020).
laryngeal carcinoma (continued). "In line with this, we described in a previous report that amplifications of CCND1 and CTTN strongly and significantly predict laryngeal cancer development." (PMID 26498851, 2015). "In this paper, we compared, using immunohistochemical analysis for cyclin D1, FADD and cortactin in a series of 106 laryngeal carcinomas which gene correlates best with lymph node metastases and increased disease-specific mortality." (PMID 18268491, 2008). "The highest percentage of Cyclin D1 positives cases (defined as CyclinD1 IRS ≥ 7) was observed in oral cavity cancer (77%, 13/17) with fewer positive cases of laryngeal cancer (46%, 16/35), hypopharyngeal cancer (39%, 9/23), and oropharyngeal cancer (36%, 28/78)." (PMID 34572957, 2021).
non-Hodgkin lymphoma (24 papers, 2010 to 2026). Distinct from Hodgkin lymphoma both morphologically and biologically, non-Hodgkin lymphoma (NHL) is characterized by the absence of Reed-Sternberg cells, can occur at any age, and usually presents as a localized or generalized lymphadenopathy associated with fever and weight loss. "Among these chromosomes, rs603965 in the cyclin D1 (CCND1) gene at the exon 4 splice site was also associated with an increased risk of Non-Hodgkin Lymphoma (NHL)." (PMID 28264017, 2017). "Cyclin D1 overexpression is nearly ubiquitous in MCL, and approximately 10%–20% of other non-Hodgkin lymphomas (NHLs) also exhibit this characteristic phenotype." (PMID 40608419, 2025). "The most frequently determined markers in the non-Hodgkin lymphoma are CD20, CD3, CD5, CD10, BCL6, BCL2, Ki-67, MYC, and cyclin D1." (PMID 40142344, 2025).
invasive breast carcinoma (23 papers, 2003 to 2024). A carcinoma that infiltrates the breast parenchyma. "Herein we show cyclin D1 abundance is increased >30-fold in the stromal fibroblasts of patients with invasive breast cancer, associated with poor outcome." (PMID 29137220, 2017). "Cyclin D1 has been reported to be a prognostic marker in invasive breast cancer and has been associated with both a less aggressive ER-positive phenotype and also with an adverse clinical outcome." (PMID 22475046, 2012). "Interestingly, CHK1 (11q24) is one of the key regulatory factors of the DNA damage checkpoint, and concurrence of CHK1 deletion and CCND1 amplification has been associated with high tumor grade in invasive breast carcinoma." (PMID 29140993, 2017). "Overexpression of cyclin D1 has been reported in invasive breast cancers and correlated with shorter disease-free survival dependent on molecular subtype." (PMID 38086377, 2023). "The goals of our study were to estimate the expression of cyclin D1 in invasive breast carcinoma, to evaluate the relation of this expression with other clinical-pathological prognostic factors and to judge the prognostic significance of cyclin D1 expression." (PMID 35942997, 2022). "Cyclin D1 over-expression has been reported in about 50% of invasive breast cancer and strongly correlates with ER levels." (PMID 31684907, 2019). "This study was designed to analyze the expression of cyclin D1 and its correlation with CCND1 amplification and their prognostic implications in invasive breast cancer." (PMID 29140993, 2017). "The expression of Cyclin D1 was usually over-expressed in some kinds of tumor cells such as the invasive breast cancer and ductal carcinoma." (PMID 24257075, 2013). "Cyclin D1 upregulation is observed in human invasive breast cancers, and our findings indicate that dysregulation of T286 phosphorylation could play a role in this phenomenon." (PMID 31484966, 2019). "In this study, we therefore examined the molecular mechanism by which calcineurin regulates cyclin D1, and asked whether the same mechanism played a role in control cell cycle in invasive breast cancer cells." (PMID 31484966, 2019). "We therefore propose that targeting site specific phosphorylation of cyclin D1 could be a potential strategy for clinical intervention of invasive breast cancer." (PMID 31484966, 2019). "We therefore propose that therapeutic targeting of cyclin D1 could be useful for the prevention and treatment of cancers, such as invasive breast cancer, where cyclin D1 is overexpressed." (PMID 31484966, 2019). "High cyclin D1 expression was identified in 94/179 (52%) of invasive breast cancers." (PMID 29140993, 2017). "Two large studies of DCIS (approximately 400 patients) have reported amplification of CCND1 in 10–12.6% of patients with pure DCIS and 14.8–17.4% of patients with DCIS associated with invasive breast cancer, with the majority of patients having amplification in the paired invasive component." (PMID 28095868, 2017). "Actually, cyclin D1 is arising as an important prognostic parameter in invasive breast cancer, but it is not employed yet in routine practice." (PMID 35942997, 2022). "We performed a retrospective study aiming to analyze the prognostic impact of cyclin D1 expression in patients with invasive breast carcinoma of no special type and its relation with clinical-pathological features." (PMID 35942997, 2022). "The results showing similar patterns of cyclin D1 and cyclin E expression in DCIS and invasive breast cancer also support that DCIS is rather similar to invasive breast cancer, and that the majority of genetic aberrations in tumour progression occur at or before the stage of DCIS." (PMID 14612904, 2003).
invasive breast carcinoma (continued). "We have also shown for the first time that seven of the known invasive breast cancer predisposition loci not previously shown to be associated with DCIS have comparable ORs for IDC and DCIS: rs4973768 (SLC4A7), rs3821902 (ATXN7), rs10995190 (ZNF365), rs554219 (CCND1), rs3757318 and rs2046210 (ESR1)." (PMID 26884359, 2016). "However, when local recurrences were split into DCIS and invasive breast cancer, similar Kaplan–Meier curves for the separate entities regarding cyclin D1 were produced (data not shown), but with less statistical significance (P=0.034 for DCIS and P=0.28 for invasive breast cancer)." (PMID 14612904, 2003). "As also observed in invasive breast cancer, there was a trend indicating that DCIS cases with high cyclin D1 were cyclin E low and oestrogen receptor-positive, whereas cyclin E high DCIS cases were cyclin D1 low and oestrogen receptor-negative." (PMID 14612904, 2003).
skin cancer (23 papers, 2008 to 2026). "On the contrary, we have found that apigenin attenuates the expression of proteins recognized as key molecules for skin cancer progression, such as Cyclin D1, Akt and Bcl2, while inducing the cleaving of Caspase 3, which plays a central role in apoptosis." (PMID 35163299, 2022). "Reduced expression of p-PI3K85, p-AKT and cyclin D1 by ERB-041 treatment has been reported in skin cancer cells." (PMID 29743815, 2018). "Meanwhile, the levels of the gene sets for epithelial-mesenchymal transition (EMT), Jak-Stat3, Cyclin D1, and Skin cancer progression were also elevated in HaCaT-Piwil2 cells, indicating neoplasia transformation." (PMID 27602489, 2016). "In skin cancer, RIG1 induces cell apoptosis by promoting pericentrosomal organelle accumulation, which is associated with the decrease in cyclin D1, cyclin E, and Bcl-XL and the increase in p21 and Bax levels." (PMID 23687991, 2013). "Studies have suggested that EGCG can also cause cell cycle arrest in A431 skin cancer cells by inhibiting Cip1/p21 with no other modifications in Kip1/p27, cyclin D1, and CDK2, but a decrease in CDK4 at low doses." (PMID 36142147, 2022). "Additionally, grape seed polyphenols decreased the UVB-induced infiltration of proinflammatory leukocytes and reduced myeloperoxidase, prostaglandin, cyclooxygenase-2, cyclin D1, and proliferating cell nuclear antigen activities in skin tumors." (PMID 36142147, 2022). "Other proteins (AKT, ERBB2, HRAS, and CCND1) are also reported to have a part in skin cancer." (PMID 34466445, 2018). "The altered expression of cyclin D1, maspin and integrin-α6 in skin of transgenic mice provides, at least in part, the molecular bases for the increased malignant potential found in the K5-IKKα skin tumors." (PMID 21755017, 2011). "Another special case seems to be skin cancer cell line LIWE, which showed downregulation after monotherapy (KI or IR) of Cyclin D1, RPTOR, and Myc in obvious contrast to the upregulation after combination of KI and IR." (PMID 34722291, 2021). "To study the role of CCHCR1 in KC proliferation and transformation, we investigated CCHCR1 protein expression by immunohistochemistry in different skin tumors in relation to EGFR, its downstream target cyclin-D1, and the hyperproliferation marker Ki67." (PMID 19551138, 2009). "Interestingly, skin cancer cell line ANST showed overall diverse behavior, regarding downregulation of Cyclin D1, Myc, and SMAD3 as well as upregulation of MARCKS and RICTOR, compared to all other tested cell lines." (PMID 34722291, 2021). "RIP assay in A375 cells provided confirmation that SMARCE1 also could bind to cyclin D1 pre-mRNA, indicating the important role of SMARCE1 in regulating the alternative splicing of cyclin D1 gene in skin cancer cells." (PMID 33670012, 2021). "The expression of cyclin D1, a critical cyclin that promotes cell proliferation, was significantly increased in SCC-25 cells expressing miR-223-3p but not in those expressing miR-376c-3p or miR-139-5p, suggesting that distinct molecular mechanisms are driven by these miRNAs in skin cancer." (PMID 39428471, 2024). "GSPs inhibited UVB-induced infiltration of proinflammatory leukocytes and the levels of myeloperoxidase (MPO), Cox-2, PGE2, Cyclin D1, and PCNA in the skin and skin tumors compared to non-GSPs-treated UVB irradiated counterpart." (PMID 24757666, 2014). "Interestingly, it was reported that in A431 skin cancer cells, EGCG did not alter the levels of p27, CDK2, and Cyclin D1 but did show inhibition of cell growth in vitro by increasing p21 and a decrease in CDK4." (PMID 37960113, 2023).
cutaneous melanoma (22 papers, 2014 to 2025). A primary melanoma arising from atypical melanocytes in the skin. "CCND1 has been associated with resistance to PD-1-targeted therapy in a Chinese population with non-cutaneous melanoma due to its effects on innate immunity." (PMID 35371031, 2022). "In a study which classed cutaneous melanomas into four genomic subtypes according to the pattern of the most prevalent significantly mutated genes, CCND1 amplification was only significantly enriched in the Triple-WT subtype." (PMID 35844619, 2022). "Meanwhile, the expression rate of cyclin D1 in cutaneous melanoma compared with benign melanocytic nevus has been discordantly reported." (PMID 35484605, 2022). "In our meta-analysis, CCND1 amplification was most frequently upregulated in acral melanomas (25.06%, 95% CI = 15.80–35.44; out of 85 cases) than in other cutaneous melanomas subtypes." (PMID 33804108, 2021). "We conclude that the four-color FISH test was highly sensitive and specific in distinguishing early-stage acral and cutaneous melanomas from dysplastic nevus in Chinese population, and the most sensitive criterion was the gain of CCND1." (PMID 32393283, 2020). "AM also has different oncogenic drivers from cutaneous melanoma, including inconstant KIT mutation rates (3–29%), CCND1 and CDK4 amplification, and deletion or mutations in different genes, such as CDK2NA, PTEN, NF1, and hTERT." (PMID 33344255, 2020). "AM has different oncogenic drivers from the cutaneous melanoma, including fewer BRAF mutations (10–23%), inconstant KIT mutation rates (3–29%), CCND1 and CDK4 amplification, and deletion or mutations in different genes, such as CDK2NA, PTEN, NF1, and hTERT." (PMID 33344255, 2020). "Our experiments showed that ESC microenvironment had the ability to inhibit proliferation and enhance apoptosis of cutaneous melanoma cells, coinciding with down‐regulation of Cyclin D1 and Cyclin B1, which resulted in a reduction in the percent of cells in G0/G1." (PMID 31173492, 2019). "In cutaneous melanoma, nuclear β‐catenin binds to TCF/LEF‐type transcription factors and consequently stimulates the expression of downstream genes, such as cyclin D1 and c‐myc." (PMID 38898581, 2024). "FAKi treatment robustly decreased TCF-4 binding to the CCND1 and C-myc promoters and induced a moderate decrease of WNT-11 and S1PR1 promoters, in concordance with the TCGA analysis in UM and cutaneous melanoma patients." (PMID 36797281, 2023).
metastatic tumors (22 papers, 2007 to 2023). "Some studies suggested that the upregulated expression of Cyclin D1 enhances metastases, whereas others found that Cyclin D1 was downregulated in metastatic tumors." (PMID 36387162, 2022). "Of note, as cohort 2 is enriched for patients with aggressive metastatic tumours, a higher percentage of CCND1 amplifications was anticipated." (PMID 30819233, 2019). "Patients with cyclin D1-overexpressing tumors survive longer but with metastatic disease after recurrence, possibly due to tamoxifen resistance produced by cyclin D1 overexpression." (PMID 29140993, 2017). "In the analysis stratified for cancer site, a significantly increased risk was found of lymph node positive (HR: 1.81 95% CI: 1.00-3.28) and non-metastatic disease (HR: 1.55; 95% CI: 1.00-2.40), as well as for cyclin D1 positive tumours (HR: 1.62 95% CI: 1.04-2.51) in the colon." (PMID 24885829, 2014). "Another explanation for the more evident beneficial prognostic effect of cyclin D1 in metastatic disease could be that cyclin D1 expression predicts response to adjuvant chemotherapy." (PMID 21888663, 2011). "The impact of cyclin D1 localisation patterns in metastatic disease is less certain." (PMID 17375037, 2007). "On the other hand, analysis of tumors (n=150), including metastatic tumors (n = 19), detected a similar positive correlation between expression of Slug and c-Jun (r = 0.39, P = 1.016e-06) and a modest positive correlation between expression of Slug and cyclin D1 (r = 0.22, P = 0.00595)." (PMID 27385093, 2016). "Of note, IHC analysis showed lower expressions of cyclin D1, c-MYC, p-IKKα/β, p-p65, and vimentin but higher expression of E-cadherin in TUBB4A KO metastatic tumors compared to scrambled metastatic tumors." (PMID 35589707, 2022). "We found seven DEGs (CCND1, EGFR, ENTPD5, HOXA10, IGF1R, MYC, and SNAI2) related to metastatic disease." (PMID 35806108, 2022). "There were rare amplifications of the D-cyclin genes (CCND1, CCND2, and CCND3); interestingly, each of these events occurred in tumors from patients with metastatic disease." (PMID 32198354, 2020). "CCND1 was amplified in 2/10 progressors at baseline and 3/8 at progression, 3/11 metastatic tumors and only 2/15 non-progressors." (PMID 27750214, 2016). "We speculate that cyclin D1 levels may be reduced in advanced terminally-differentiated metastatic tumors, as cells at this stage no longer require cyclin D1’s regulatory effects on proliferation and differentiation." (PMID 24213463, 2012).